FXYD1 (FXYD domain containing ion transport regulator 1)
Description:
Associates with and regulates the activity of the sodium/potassium-transporting ATPase (NKA) which transports Na(+) out of the cell and K(+) into the cell. Inhibits NKA activity in its unphosphorylated state and stimulates activity when phosphorylated. Reduces glutathionylation of the NKA beta-1 subunit ATP1B1, thus reversing glutathionylation-mediated inhibition of ATP1B1. Contributes to female sexual development by maintaining the excitability of neurons which secrete gonadotropin-releasing hormone.
Synonyms: PLM
Tractability: Antibody: its Gene Ontology location is reachable by antibodies, with high confidence; UniProt places it where antibodies can reach, with medium confidence; UniProt predicts a signal peptide or a membrane-spanning region.
Gene: Protein-coding gene on chromosome 19 (35,137,159 to 35,143,109, forward strand). Ensembl gene ENSG00000266964.
Subcellular location: Cell membrane, sarcolemma; Apical cell membrane; Membrane, caveola; Cell membrane, sarcolemma, T-tubule
Subcellular location (Human Protein Atlas): Cytosol; Nucleoplasm; Nucleoli
Pathways (Reactome):
Disease: Potential therapeutics for SARS
Muscle contraction: Ion homeostasis
Transport of small molecules: Ion transport by P-type ATPases
Gene Ontology:
Molecular function: chloride channel activity; sodium channel regulator activity; transmembrane transporter binding; ion channel regulator activity
Biological process: chloride transport; establishment or maintenance of transmembrane electrochemical gradient; intracellular potassium ion homeostasis; intracellular sodium ion homeostasis; muscle contraction; negative regulation of protein glutathionylation; positive regulation of sodium ion export across plasma membrane; potassium ion import across plasma membrane; proton transmembrane transport; regulation of cardiac muscle cell membrane potential; regulation of heart contraction; sodium ion export across plasma membrane; chloride transmembrane transport; monoatomic ion transport; regulation of monoatomic ion transport; regulation of sodium ion transmembrane transport
Cellular component: apical plasma membrane; caveola; intercalated disc; plasma membrane; sarcolemma; sodium:potassium-exchanging ATPase complex; T-tubule; membrane
Genetic constraint (gnomAD): Loss-of-function variants: 5 observed, 12.66 expected, observed/expected ratio (o/e) 0.39, 90% interval 0.2 to 0.83. The upper end of that interval is the gene's LOEUF score, 0.83, which puts it in group 3 of 6, group 1 being the genes least tolerant of losing a copy. Missense variants: 82 observed, 93.71 expected, observed/expected ratio (o/e) 0.87, 90% interval 0.73 to 1.05. Synonymous variants: 45 observed, 35.19 expected, observed/expected ratio (o/e) 1.28, 90% interval 1.01 to 1.64.
Homologues: Orthologues: macaque FXYD1 (95% identical), dog FXYD1 (90% identical), chimpanzee FXYD1 (87% identical), mouse Fxyd1 (83% identical), guinea pig FXYD1 (78% identical), rat Fxyd1 (59% identical). Paralogues in human: FXYD6 (47% identical), FXYD3 (30% identical), FXYD2 (28% identical), FXYD4 (28% identical), FXYD7 (27% identical), FXYD5 (25% identical).
Diseases named in the same sentence as FXYD1 in open-access papers:
FXYD1 is named in the same sentence as 22 diseases in open-access papers, as found by Europe PMC text mining. Sharing a sentence is not in itself a finding about the gene and the disease. The quoted sentences say what the papers report.
breast cancer (5 papers, 2022 to 2026). A primary or metastatic malignant neoplasm involving the breast. "Here, FXYD1 is identified as a significantly downregulated gene in breast cancer tissues, and low FXYD1 expression is associated with unfavorable patient prognosis." (PMID 41782411, 2026). "The FXYD (FXYD domain-containing ion transport regulator) family, classically known for ion transport regulation, has recently been implicated in oncogenesis; however, the role of its founding member, FXYD1, in breast cancer remains unclear." (PMID 41782411, 2026). "FXYD1 is also known as phospholemann (PLM), FXYD2 as γ, FXYD3 as Mat-8 (Mammary tumor marker), FXYD4 as CHIF (channel inducing factor), FXYD5 as dyshaderin or RIC (related to ion channel), and FXYD6 as phosphohippolin." (PMID 38892309, 2024). "This suggested that HOXC10, FXYD1, MT1X, and IGF2 may play an important role in the development of luminal A breast cancer under the regulation of HOXC-AS3, AC020907.2, AC026461.1, and AC132217.1." (PMID 35692369, 2022). "Collectively, our findings uncover a previously unrecognized FXYD1-MAEA-DDX5 axis that inhibits Wnt/β-catenin signaling through a non-canonical ubiquitin-proteasome pathway, establishing FXYD1 as a tumor suppressor and potential prognostic biomarker and therapeutic target in breast cancer." (PMID 41782411, 2026).
heart failure (3 papers, 2021 to 2025). Inability of the heart to pump blood at an adequate rate to meet tissue metabolic requirements. "Several members of the FXYD family have been linked to major human diseases, including heart failure (FXYD1), hypomagnesemia (FXYD2), cancer (FXYD3, FXYD5), and schizophrenia (FXYD6), making them attractive specific targets for future therapies." (PMID 40428357, 2025).
Rett syndrome (3 papers, 2007 to 2022). A severe neurodevelopmental disorder affecting the central nervous system.
schizophrenia (3 papers, 2022 to 2025). A major psychotic disorder characterized by abnormalities in the perception or expression of reality. "Two pathogenic de novo variants in ATP1A3 and missense variants in FXYD gene family (FXYD1, FXYD2) were also identified in 17 sporadic cases of childhood onset schizophrenia using whole exome sequencing." (PMID 36384485, 2022).
cardiac hypertrophy (2 papers, 2007 to 2017). "Overexpression of FXYD1 in adult cardiac myocytes acutely alters contractility as a function of extracellular Ca+ concentration, and Fxyd1 knock-out mice have cardiac hypertrophy." (PMID 17584923, 2007).
glioma (2 papers, 2023 to 2025). A benign or malignant brain and spinal cord tumor that arises from glial cells (astrocytes, oligodendrocytes, ependymal cells). "The differential expression analysis results showed that the mRNA expression levels of FXYD1, ZCCHC12, and PDE2A were highly expressed in normal brain tissues, while the other six genes were significantly upregulated in glioma samples." (PMID 41438761, 2025). "On the one hand, FXYD1 was downregulated in almost all cancers indicating a promising pan‐cancer biomarker in the future, while FXYD2‐FXYD5 failed to exhibit the specific tendency in gliomas compared with other cancers." (PMID 38093622, 2023).
ischaemia (2 papers, 2015 to 2016). "Along with PKC, PKA may catalyze phosphorylation of PLM at Ser68 in response to ischemia or β adrenergic stimulation causing release of the inhibitory action of association of the FXYD1 subunit with the Na,K-ATPase." (PMID 27531981, 2016).
dementia (1 paper, 2018). Loss of intellectual abilities interfering with an individual's social and occupational functions. "MLC1 and FXYD1 were chosen from the larger pool of novel gene candidates based on the associations identified with dementia status and tau pathology." (PMID 30120299, 2018). "Evaluation of this microarray data revealed strikingly consistent associations with the Allen Aging, Dementia, and TBI dataset for each of the four genes (AQP4, DTNA, MLC1, FXYD1)." (PMID 30120299, 2018). "In contrast, FXYD1 expression does not predict dementia status, but is strongly associated with temporal cortical P-tau levels." (PMID 30120299, 2018).
cancer (7 papers, 2017 to 2025). A tumor composed of atypical neoplastic, often pleomorphic cells that invade other tissues. "BEST1, UCP2 and FXYD1 are genes associated with nutrient and energy transport that have previously been identified as upregulated in cancer cells." (PMID 32051475, 2020). "Based on the obtained results, we hypothesize that, in the normal tissue, the lower level of cg23866403 loci methylation in the FXYD1 gene promoter results in a shortened spatial distance to the gene enhancer, and, as a result, FXYD1 increased expression compared to the cancer tissue." (PMID 40724805, 2025). "FXYD1, FXYD3, FXYD6 and FXYD7 were significantly downregulated in cancer samples, while FXYD4 and FXYD5 were markedly overexpressed." (PMID 34270462, 2021).
tumor (5 papers, 2011 to 2026). "More than half of the genes were not DE in any tumor type, while seven genes (C7, ADH1B, HSPB6, FXYD1, PLAC9, TMEM132A and ASF1B) were DE in all tumor types." (PMID 26655252, 2016). "Analysis of the TIMER database demonstrated that FXYD1, FXYD6 and FXYD7 had significantly negative associations with tumor purity, while these genes had markedly positive correlations with CD4+ T cells, macrophages and dendritic cells." (PMID 34270462, 2021). "In addition, FXYD1 and HSPB6 were overexpressed only in KIRC and LIHC, respectively, whereas they were downregulated in other types of tumor." (PMID 26655252, 2016).
neurodevelopmental disorder (2 papers, 2020 to 2022). A behavioral and cognitive disorder with onset during the developmental period that involves impaired or aberrant development of intellectual, motor, or social functions. "In conclusion, we found, for the first time, that IGF-1 can relieve the symptoms of RTT by down-regulating the phosphorylation level of FXYD1, which provides a new therapeutic mechanism for a large class of neurodevelopmental disorders." (PMID 32063830, 2020).
neurodegenerative disease (1 paper, 2023). A disorder of the central nervous system characterized by gradual and progressive loss of neural tissue and neurologic function. "However, we still do not know the roles of many key drivers identified in this study in the development of neurodegenerative diseases, such as REPS2 and FXYD1." (PMID 37284017, 2023).
FXYD1 also shares sentences with these, for which no sentence is quoted: colorectal cancer (3 papers); Arrhythmia (2); cardiac disease (2); breast tumors (1); cardiovascular disease (1); colon cancer (1); Hypomagnesemia (1); long QT syndrome 12 (1); movement disorder (1); Timothy syndrome (1).